PRELID2 (PRELI domain containing 2)
Synonyms: MGC21644; FLJ38376
Tractability: PROTAC: ubiquitination databases record sites on it.
Gene: Protein-coding gene on chromosome 5 (145,471,799 to 145,835,369, reverse strand). Ensembl gene ENSG00000186314.
Subcellular location (Human Protein Atlas): Nucleoplasm
Gene Ontology:
Molecular function: phosphatidic acid transfer activity
Biological process: phospholipid transport
Cellular component: mitochondrial intermembrane space
Genetic constraint (gnomAD): Loss-of-function variants: 8 observed, 8.55 expected, observed/expected ratio (o/e) 0.94, 90% interval 0.55 to 1.64. That is too few expected variants to judge how well the gene tolerates losing a copy. Missense variants: 97 observed, 93.82 expected, observed/expected ratio (o/e) 1.03, 90% interval 0.88 to 1.22. Synonymous variants: 37 observed, 33.92 expected, observed/expected ratio (o/e) 1.09, 90% interval 0.84 to 1.43.
Homologues: Orthologues: chimpanzee PRELID2 (100% identical), dog PRELID2 (95% identical), guinea pig PRELID2 (92% identical), pig PRELID2 (90% identical), mouse Prelid2 (89% identical), rat Prelid2 (88% identical), macaque PRELID2 (77% identical), tropical clawed frog prelid2 (60% identical). Paralogues in human: PRELID3A (25% identical), PRELID3B (24% identical), PRELID1 (20% identical).
Diseases named in the same sentence as PRELID2 in open-access papers:
PRELID2 is named in the same sentence as 11 diseases in open-access papers, as found by Europe PMC text mining. Sharing a sentence is not in itself a finding about the gene and the disease. The quoted sentences say what the papers report.
glioma (1 paper, 2022). A benign or malignant brain and spinal cord tumor that arises from glial cells (astrocytes, oligodendrocytes, ependymal cells). "Patients with glioma exhibiting elevated GNG5 expression have a shorter survival time, and patients with head and neck squamous cell carcinoma and elevated PRELID2 expression have a poor prognosis." (PMID 35968507, 2022).
liver cancer (1 paper, 2023). An epithelial or non-epithelial malignant neoplasm that arises from the liver. "Moreover, our results showed that PRELID2 promotes the proliferation and metastasis of liver cancer cells by enhancing ROS generation, which is similar to the function of PRELID1 in increasing ROS production." (PMID 38124228, 2023).
lung carcinoma (1 paper, 2023). "Another study found that PRELID2 can be targeted and inhibited by miR-486-5p, which exerts a tumor-suppressive effect in several human cancers, including lung cancer, prostate cancer, and CRC." (PMID 38124228, 2023).
Obesity (1 paper, 2020). Accumulation of substantial excess body fat. "Only six out of the 81 mitochondrial protein-encoding genes showed higher expression in the obesity-risk genotype (SEPT4, PYCR1, PRELID2, CPT1A, MTHFD1L, and FKBP10)." (PMID 32316277, 2020).
cancer (1 paper, 2023). A tumor composed of atypical neoplastic, often pleomorphic cells that invade other tissues. "However, the function of PRELID2 in cancer is still not entirely clear." (PMID 38124228, 2023).
cardiovascular disease (1 paper, 2012). "Using this approach, we have identified four candidate genes (EBF1, PPP2R2B, PRELID2, and SPOCK1) that may represent novel cardiovascular disease risk genes mediated through LDL cholesterol pathways." (PMID 22369142, 2012).
tumor (1 paper, 2023). "Furthermore, a high level of PRELID2 was closely associated with tumor grade (P < 0.01 or P < 0.001)." (PMID 38124228, 2023). "In our study, we have revealed for the first time the tumor-promoting effect of PRELID2 in HCC." (PMID 38124228, 2023). "Additionally, we determined the tumor-promoting role of Prelid2 in vivo by constructing KLC primary cells with stable Prelid2 knockdown (LV-shPrelid2) (P < 0.001)." (PMID 38124228, 2023). "In line with the in vitro cell assays, we found Prelid2 knockdown markedly decreased the tumor volume and weight of HCC xenograft (P < 0.01), indicating that Fbxl6 elevation synergizes with KrasG12D to drive HCC tumorigenesis via the upregulation of Prelid2." (PMID 38124228, 2023). "Moreover, PRELID2 was positively correlated with TNM stage (P < 0.001), tumor size (P = 0.013), tumor metastasis (P < 0.01), vascular thrombosis (P < 0.001) and recurrence (P < 0.001)." (PMID 38124228, 2023).
PRELID2 also shares sentences with these, for which no sentence is quoted: genetic disease (1 paper); head and neck squamous cell carcinoma (1); nasopharyngeal carcinoma (1); prostate carcinoma (1).